Y_RNA (Y RNA )
Gene: Miscellaneous RNA gene on chromosome 2 (177,194,983 to 177,195,095, forward strand). Ensembl gene ENSG00000201102.
Homologues: Orthologues: chimpanzee Y_RNA (99% identical), macaque Y_RNA (90% identical). Paralogues in human: RNY1 (87% identical), Y_RNA (86% identical), Y_RNA (85% identical), Y_RNA (84% identical), RNY1P8 (83% identical), Y_RNA (83% identical), RNY1P11 (82% identical), Y_RNA (82% identical), Y_RNA (81% identical), Y_RNA (80% identical), RNY1P7 (79% identical), Y_RNA (79% identical), and 98 more.